WT1 (WT1 transcription factor)
Diseases named in the same sentence as WT1 in open-access papers (continued):
Sharing a sentence is not in itself a finding about the gene and the disease.
Nephropathy (continued). "Although no cystic appearance has previously been reported in children with WT1 p.Arg467Gln, our findings raise the possibility that the COL4A4 variant may contribute to a cystic phenotype in WT1 nephropathy." (PMID 41450889, 2025). "The situation of 15 children with WT1 gene mutation nephropathy in our center." (PMID 37576146, 2023). "In conclusion, the molecular biological characteristics of WT1 gene mutation-related nephropathy determine the clinical type, pathological characteristics, and renal survival time of the disease, and there is a high correlation between genotype and clinical phenotype." (PMID 37576146, 2023). "The phenotypic and genotypic heterogeneity of WT1-associated disease presents challenges for clinicians, with patient care impacted due to the very different phenotypic continua, tumor risks, and surveillance programs required for FS and other nephropathies." (PMID 35211794, 2022). "The first variant is a WT1 missense mutation: NM_024426.6; exon 9; c.1400G>A (p.Arg467Gln), affecting a known hotspot residue within the third zinc finger domain and previously associated with severe WT1-related nephropathy (formerly classified as DDS subtype)." (PMID 41450889, 2025). "Therefore, Sphk2 may be a potential new target for the treatment of WT1 mutation-related nephropathy." (PMID 37576146, 2023). "The unique feature of our case is bilateral kidney enlargement with multiple microcysts, representing a polycystic appearance that is unusual for WT1-related nephropathy." (PMID 41450889, 2025). "We report a neonate with WT1-related nephropathy presenting with bilaterally enlarged echogenic kidneys resembling the pattern of polycystic kidney, without hepatic abnormalities or extrarenal cysts." (PMID 41450889, 2025). "This case report aims to offer a new perspective on DDS with novel WT1 and ACTN4 co-mutations, providing insight into the progression of nephropathy." (PMID 40890712, 2025). "WT1 disorders leading to a spectrum of phenotypes are now integrated into a single entity of “WT1-related nephropathy”." (PMID 41450889, 2025). "In terms of nosology, the WT-1 disorders have been integrated into an entity known as “WT1-related nephropathy” based on the molecular diagnosis." (PMID 41450889, 2025). "To date, this study contains the largest case cohort of children with WT1 mutant nephropathy in China." (PMID 37576146, 2023). "Proteins that comprise the kidney tissue, such as nephrin, podocin, Wilms' tumor-1 (WT1), and megalin, can indicate early kidney damage when present in the urine prior to the appearance of albuminuria." (PMID 36266308, 2022). "Intriguingly, the facilitating effects of miR-193a on nephropathy were, to some extent, dependent on suppression of Wilm’s tumor protein (WT1), which was usually suggestive of quantitatively reduced podocytes and damaged glomerular filtration barrier." (PMID 31352863, 2019). "Our data show that the attenuation of transcription of WT-1 and nephrin in adriamycin-induced nephropathy were restored by treatment with gemigliptin." (PMID 28326327, 2017). "Our case suggests that the cystic change may manifest as a subtype of WT1-related nephropathy, particularly when the second modifier, such as COL4A4 variant, coexists." (PMID 41450889, 2025). "What’s more, two podocytes located downstream of miR-193 (i.e., WT1 and PODXL) were also nephropathy-relevant." (PMID 31352863, 2019). "Thus, quantification of WT1 and ACE mRNAs in blood exosomes reflects the degree of albuminuria and the severity of nephropathy in DN patients, suggesting these mRNAs could serve as predictors of DN progression." (PMID 34246281, 2021). "This study aimed to assess the expression levels of ACE, ELMO1, and WT1 mRNAs in the blood extracellular vesicles (EVs) of DN patients and diabetic patients without nephropathy (DM group) in comparison to healthy controls and investigate their correlations with the severity of DN." (PMID 34246281, 2021).
focal segmental glomerulosclerosis (24 papers, 2012 to 2025). A renal disorder characterized by sclerotic lesions in the glomeruli. "Mutations involving WT1 have been associated with various glomerulopathies including focal segmental glomerulosclerosis (FSGS) and diffuse mesangial sclerosis (DMS)." (PMID 35211794, 2022). "Moreover, pathogenic WT1 gene variants cause kidney diseases, such as diffuse mesangial sclerosis and focal segmental glomerulosclerosis (FSGS), which can lead to end-stage kidney disease (ESKD)." (PMID 38877226, 2024). "A loss of renal WT1 expression may initiate a catastrophic collapse of the entire podocyte-stabilizing system, leading to several glomerular diseases such as focal segmental glomerulosclerosis (FSGS) and diabetic nephropathy (DN)." (PMID 37795410, 2023). "WT1 was also reported to implicate in focal segmental glomerulosclerosis via mediating miR-193a." (PMID 32322310, 2020). "However, upon follow-up the diagnosis of progressive renal failure based on focal segmental glomerulosclerosis, prompted analysis of the WT1 gene." (PMID 22815844, 2012). "Interestingly, patients carrying a deleterious variant in PAX2 may also present with steroid resistant nephrotic syndrome (SRNS) and focal segmental glomerulosclerosis (FSGS), similar to patients with a deleterious variant in WT1." (PMID 33625646, 2021). "In focal segmental glomerulosclerosis (FSGS), a disease with significant podocyte damage, Wilm’s tumor-1 (WT-1), a transcriptional factor required for normal kidney development, was examined in urinary exosomes as a marker for podocyte damage." (PMID 32429335, 2020). "In the podocytes of patients with focal segmental glomerulosclerosis (FSGS), the expression of miR-193a was induced, which in turn inhibited the expression of WT1, modulating the expression of genes critical for podocyte architecture." (PMID 28299339, 2017). "Wilms Tumor 1 (WT1) is constitutively expressed on podocytes of healthy adult kidneys, and its expression decreases in kidney biopsies of patients with primary focal segmental glomerulosclerosis (FSGS)." (PMID 27376269, 2016). "Moreover, transgenic expression of miR-193a in mice induces focal segmental glomerulosclerosis (FSGS) with downregulation of WT1, and miR-193a is overexpressed in the podocytes of patients with FSGS." (PMID 25329154, 2014).
malignant mesothelioma (23 papers, 2013 to 2025). A malignant neoplasm of the pleura or peritoneum, arising from mesothelial cells. "The expression of WT-1, observed in a single tested case, also presents a potential diagnostic challenge in differentiation from a malignant mesothelioma, in particular in a pleural-based disease." (PMID 40909976, 2025). "The positivity of mesothelial markers, such as WT1, calretinin, podoplanin and HBME1, along with clinical–radiological findings, helps to distinguish this peculiar variant of malignant mesothelioma from a metastatic adenocarcinoma from another site." (PMID 35204459, 2022). "Generally, the immunoreactivity for mesothelial markers including calretinin, CK5/6, WT1, and D2–40 is helpful for distinguishing malignant mesothelioma from other malignant tumors proliferating in the pleura." (PMID 34333253, 2021). "Both LNT- and LFA-induced tumors, involving the chest wall, diaphragm, and pericardium, stained positive for the mesothelial markers pan-cytokeratin and WT1 and exhibited histopathology consistent with malignant mesothelioma." (PMID 29112861, 2017). "This is further supported by the expression of WT1, calretinin and D2–40, and rarely malignant mesotheliomas may harbour STK11 alterations." (PMID 38376618, 2024). "Wilms tumor 1 (WT1)/AE1/AE3, claudin 4, and BRCA1‐associated protein 1 (BAP1) immunostains are useful new tools that have been proposed for the distinction between Malignant Mesothelioma and benign mesothelial reactions." (PMID 36069384, 2022). "One study from the National Cancer Institute in Bethesda, Maryland, evaluated the reactivity of several IHC markers, calretinin, keratin cocktail (AE1/AE3), and WT-1 immunoreactivity to differentiate malignant mesothelioma from other fibroblastic/myofibroblastic neoplasms." (PMID 36171577, 2022). "Histopathologic examination confirmed malignant mesothelioma of epithelioid type, supported by immunohistochemical reactivity for calretinin, cytokeratin 7 (CK7), cytokeratin 5/6 (CK5/6), pan-cytokeratin (PanCK), Wilms tumor 1 (WT1), and loss of BRCA1-associated protein-1 (BAP1)." (PMID 40978995, 2025). "In veterinary field, vimentin, E-cadherin, pancytokeratin, Wilms tumor 1 (WT1), MUC-1, and calretinin were used to differentiate between reactive mesothelial cells, malignant mesotheliomas, and adenocarcinomas in large felids only through post-mortem." (PMID 37480011, 2023). "More organ-specific antibodies will be added such as ER, PR, PAX8 (Müllerian tumours), TTF1 (lung, thyroid), GATA3 (breast, urothelial), CDX2 (gastrointestinal) and Calretinin, BerEP4, WT1 and CK5/6 (malignant mesothelioma)." (PMID 29621151, 2018). "An early study comparatively evaluated WT1 protein levels, using three non-commercially available monoclonal antibodies, in malignant mesotheliomas, as opposed to primary lung tumors and metastatic pleural lesions." (PMID 35453662, 2022). "A focal OSCAR keratin and WT-1 expression in the absence of carcinoma markers, a malignant mesothelioma, biphasic type was diagnosed." (PMID 30109162, 2018). "Previous studies showed that, Calretinin, Wilms tumor protein 1 (WT-1), HBME-1, D2-40 (podoplanin), Carcinoembryonic antigen (CEA), Napsin-A and Thyroid transcription factor 1 (TTF-1) are immunocytochemical indicators for distinguishing malignant mesothelioma from lung adenocarcinoma." (PMID 32731396, 2020). "The tumor cells were also negative for SALL4 and octamer-binding transcription factor 3/4 (OCT3/4), excluding germ cell tumors, and negative for Wilms’ tumor 1 (WT1), calretinin, and D240, excluding malignant mesothelioma." (PMID 40337377, 2025).
diabetes (22 papers, 2006 to 2025). "We also confirmed the rise in WT1 protein levels in the uE of rats after diabetes-induced kidney injury; the rise was strongly associated with uACR." (PMID 37795410, 2023). "For example, Wilm’s tumor-1 (WT-1) in urine exosomes can be used as a diagnostic indicator for diabetes." (PMID 36172178, 2022). "Furthermore, Wilms tumor protein‌‌ 1 (WT1) staining demonstrated that podocyte‐specific RIPK3 KO reduced podocyte loss caused by diabetes." (PMID 40539374, 2025). "The number of podocytes per glomerulus (WT1-positive cells) was comparable among untreated control, untreated KO and diabetic control mice, but IRE1α KO mice after 6 months of diabetes showed a significant reduction of podocytes." (PMID 38778209, 2024). "The decreased podocytes were confirmed by WT1 immunohistochemistry staining, indicating significant podocyte injuries in the DN mice compared with the non-diabetes (ND) mice." (PMID 38139429, 2023). "WT1 was analyzed in uE from humans and Wistar rats (before and after the 9th week of diabetes, n = 20)." (PMID 37795410, 2023). "Embryos from dams with maternal diabetes had a significantly lower number of Wt1‐positive epicardial cells compared to those of controls." (PMID 31211496, 2019). "Meanwhile, it reduced the diabetes-induced podocyte injury by increasing WT1 and nephrin expression." (PMID 29904053, 2018). "Mice with STZ-induced diabetes exhibited glomerular matrix hyperplasia and decreased numbers of podocyte nucleus-specific WT1-positive cells." (PMID 30158674, 2018). "The results of immunohistochemical staining and qRT-PCR analysis show that NXT was able to partially restore diabetes-reduced WT1 protein and mRNA expression." (PMID 29904053, 2018). "The expression of WT1 protein in urinary exosomes from spot urine samples of type-1 diabetes mellitus patients (n = 48) and healthy controls (n = 25) were analyzed." (PMID 23544132, 2013). "Rats with diabetes showed a reduction in podocyte number as determined by staining for WT1 and GLEPP1." (PMID 16539708, 2006). "We found diabetes inhibited the expression of WT1 and promoted expression of Caspase-3." (PMID 33162804, 2020). "In addition, the expression of WT1 protein in urinary exosomes from spot urine samples of patients with type 1 diabetes mellitus (n = 48) and healthy controls (n = 25) was analyzed." (PMID 32582146, 2020). "Moreover, the reduction in the number of WT1-positive podocytes is alleviated in Smad3+/-;db/db mice compared with db/db mice, suggesting that Smad3 activation is involved in podocyte damage in diabetes mellitus." (PMID 31150422, 2019). "Since glucose-induced ROS have been shown to be a major contributor to podocyte apoptosis and depletion in experimental diabetes leading to diabetic nephropathy, we also measured the extent of WT-1 staining (a podocyte-specific nuclei marker) in the glomeruli of all groups in this study." (PMID 23874911, 2013). "In addition to nephrin, other proteins can also be suppressed in the renal tissue and/or be increased in the urine of diabetes subjects, including podocin, podocalyxin, synaptopodin, and Wilms’ tumor protein (WT-1), a phenotypic marker of mature podocytes." (PMID 24103534, 2013). "The number of podocytes per glomerular section and the podocyte density in glomeruli from rats and mice with streptozotocin (STZ)-diabetes mellitus was determined at several time points based on detection of the glomerular podocyte specific antigens, WT-1 and GLEPP1." (PMID 16539708, 2006). "The coefficients for each parameter were as follows: 0.4029 for abnormal NT-pro BNP, 0.1706 for history of diabetes, 0.6376 for NPM1, 0.0294 for FLT3, 0.0383 for Ras, 0.1220 for WT1, 0.5206 for JAK2, 0.0055 for WBC, 0.0942 for RBC, and − 0.0007 for EF." (PMID 38273254, 2024).
myocardial infarction (22 papers, 2012 to 2025). Gross necrosis of the myocardium, as a result of interruption of the blood supply to the area, as in coronary thrombosis. "The response was linked to Wills tumour gene 1 (Wt1) expression in the epicardial layer bordering the myocardial infarction, inducing a proliferative and neovascularization response." (PMID 31752983, 2019). "In the present experiments, we investigated whether myocardial infarction (MI) was able to reinstate the expression of Wilms’ tumor factor 1 (WT1) as a key hallmark of fetal reprograming in the pericardial adipose-derived stem cells (pADSC)." (PMID 30103817, 2018). "In addition, it needs to be clarified whether WT1 re-expression is related to an induction of proliferation in order to compensate for the cardiomyocyte loss after myocardial infarction." (PMID 39768169, 2024). "In this study, we conducted a comprehensive analysis of WT1 expression in murine models of experimental myocardial infarction, induced by left coronary artery ligation, in the acute phase (48-72 hours post-MI) and the reparative phase (3 weeks)." (PMID 40585983, 2025). "Nevertheless, enhanced immune invasion combined with reduced angiogenesis after myocardial infarction are more likely to account for the severe phenotype observed in animals with conditional Wt1 knockout in endothelial, hematopoietic-derived and myeloid cells." (PMID 40585983, 2025). "WT1 (GFP) marked the majority of endothelial cells (CD31+CD45-) in the heart after myocardial infarction, was expressed in around 50% of the progenitor cell populations and more than half of MDSCs (CD45+Ly6-G+CD11b+)." (PMID 40585983, 2025). "In order to quantify WT1 contribution to these different cell populations after acute myocardial infarction, we made use of Wt1GFP knock in mice where WT1 expression is reflected by cytoplasmic GFP expression." (PMID 40585983, 2025). "Subsequent ImageStream® analyses demonstrated in agreement with our previous findings that the number of WT1 expressing cells in the heart following myocardial infarction is strongly upregulated." (PMID 40585983, 2025). "In a different reporter system, a significant increase in Wt1 expression and proliferation in the epicardium shortly after myocardial infarction was observed and the formation of a Wt1-lineage-positive subepicardial mesenchyme cell population described." (PMID 39768169, 2024). "In response to injury, the epicardium re-activates the expression of WT1, but little is known about the roles it plays in cardiomyocytes, which are the main cell type affected after myocardial infarction." (PMID 39768169, 2024). "This indicates that WT1 is involved in the formation of novel coronary vessels upon myocardial infarction through stimulation by hypoxia, the reduced tissue oxygen supply." (PMID 39768169, 2024). "Upregulation of WT1 expression in the adult myocardium has been reported to promote vascularization and cardiac remodeling following myocardial infarction." (PMID 37072781, 2023). "WT1 is normally expressed at low levels in these cells, and a significant upregulation has been reported after myocardial infarction." (PMID 37233178, 2023). "WT1-expressing ADSC (eGFP:WT1) were irreversibly labeled in transgenic mice (WT1-iCre/Gt(ROSA)26Sor-eGFP) primed with myocardial infarction." (PMID 35101092, 2022). "In 2011, a reactivation of Wt1 expression after myocardial infarction resulting in cardiomyocyte restitution has been proposed." (PMID 34299295, 2021). "For these reasons, we measured endogenous Wt1 mRNA levels and used a sensitive immunohistochemistry approach to characterize Wt1 expressing cells during cardiac development, in the adult, and during repair after myocardial infarction." (PMID 33919406, 2021). "Given the distance to the epicardium, where we detected Wt1-positive cardiomyocytes already 48 h after myocardial infarction, it is unlikely that these cells are directly epicardium-derived." (PMID 33919406, 2021).